RSU1 (Ras suppressor protein 1)
Diseases named in the same sentence as RSU1 in open-access papers (continued):
Sharing a sentence is not in itself a finding about the gene and the disease.
Hypertension (1 paper, 2024). The presence of chronic increased pressure in the systemic arterial system. "Given the elevated expression of GFI1B, MYLK, and RSU1 in hypertension, we performed GSEA to focus on their functional enrichment in this context." (PMID 39519602, 2024). "We previously discussed the relationship between GFI1B, MYLK, and RSU1 and hypertension, noting their roles in vascular resistance and renal metabolic pathways." (PMID 39519602, 2024). "Three machine learning algorithms identified five biomarkers associated with hypertension: calmodulin 3 (CALM3), cluster of differentiation 9 (CD9), growth factor independence 1B transcriptional repressor (GFI1B), myosin light chain kinase (MYLK), and Ras suppressor-1 (RSU1)." (PMID 39519602, 2024). "The intersection of the three machine learning algorithms identified five genes as potential key biomarkers for hypertension: calmodulin 3 (CLAM3), CD9, growth factor independent 1B transcriptional repressor (GFI1B), myosin light chain kinase (MYLK), and Ras Suppressor Protein 1 (RSU1)." (PMID 39519602, 2024).
hypertrophic cardiomyopathy (1 paper, 2025). A condition in which the myocardium is hypertrophied without an obvious cause. "Proteomic profiling identified a set of six proteins with predictive value for SCD in patients with hypertrophic cardiomyopathy (HCM): thrombospondin-1 (THBS1), complement C3 (C3), aldolase A (ALDOA), Ras suppressor protein 1 (RSU1), glutathione S-transferase omega 1 (GSTO1), and talin-1 (TLN1)." (PMID 40725061, 2025).
lung carcinoma (1 paper, 2022). "Overexpression of ILK in lung cancer cells results in the upregulation of PINCH1, β-parvin, and Ras suppressor protein 1 (RSU1) expression, while pharmacologic inhibition of ILK in KRAS-mutant lung cancer cells suppressed cell growth, migration, and EMT." (PMID 35804980, 2022).
metastatic cancer (1 paper, 2020). A carcinoma which has spread from the original site of growth to another anatomic site. "Future studies will shed some light on the potential of RSU1 as a therapeutic target against metastatic cancer." (PMID 32517326, 2020).
prostate tumors (1 paper, 2020). "It is known that miR-409-5p activates the AKT pathway, and via the depletion of RSU1, promotes exosome-mediated prostate tumors." (PMID 32751711, 2020).
psoriasis (1 paper, 2024). An autoimmune condition characterized by red, well-delineated plaques with silvery scales that are usually on the extensor surfaces and scalp. "Researchers from the Yonsei University College of Medicine have found such biomarkers as psoriasis-associated fatty acid-binding protein (FABP5), moesin, and Rho-GDP dissociation inhibitor (RhoGDI), thioredoxin domain-containing protein 5 (TXNDC5), Ras suppressor protein-1 (RSU1) and vimentin." (PMID 39493718, 2024).
urachal carcinoma (1 paper, 2018). "This suggests a regulatory role of RSU1 and AIFM2 in urachal carcinoma metastases." (PMID 29901861, 2018).
cancer (19 papers, 2013 to 2024). A tumor composed of atypical neoplastic, often pleomorphic cells that invade other tissues. "Although RSU-1 was connected to Ras-mediated oncogenic transformation, its expression in cancer tissues, and its association to metastasis are still vague." (PMID 31296919, 2019). "Although RSU-1 was linked to Ras-dependent oncogenic transformation and was shown to have anti-tumorigenic effects suppressing cancer cell growth, its expression level and role in cancer has yet to be defined." (PMID 31296919, 2019). "RSU-1 is a cell–ECM adhesion protein that has been recently linked to BC metastasis being upregulated in BC samples while its depletion severely impairs cancer cell invasion in vitro." (PMID 30621163, 2019). "Taken all together, these results suggest that RSU1 is positively involved in cancer cell spreading, directional migration, and invasion through ECM." (PMID 33853759, 2021). "Although Rsu1 was identified as the suppressor of Ras, the widely characterized oncogene, Rsu1 is upregulated in various cancers." (PMID 33587032, 2021). "The depletion of Rsu1 in the different cancer cells led to different influences on the cell motility, raising a more puzzling question about the Rsu1’s role in regulating cell behaviors." (PMID 33587032, 2021). "Thirdly, the presence of the truncated RSU1 isoform should be further investigated in other cancer types and its interplay with the full length RSU1 needs to be better defined." (PMID 32517326, 2020). "RSU-1 isoforms are tightly regulated in cancer, both having metastasis-promoting properties through activation of uPA and by inducing the expression of PINCH-ILK-PARVA complex." (PMID 31296919, 2019). "Beyond cancer cell proliferation, RSU-1 has been also documented to play a crucial role in cancer cell migration and invasion both of which are fundamental steps in the metastatic process." (PMID 31123330, 2019). "In fact, identification of blocking peptides or inhibitors of RSU-1 has the potential to lead to novel therapeutic approaches that will ultimately improve overall survival of cancer patients dealing directly with metastasis." (PMID 31296919, 2019). "Although, RSU-1 was originally identified as suppressor of Ras-dependent oncogenic transformation, little is known regarding its expression and role in cancer." (PMID 28423706, 2017). "It is concerning because recent research has revealed a link between high levels of SEC23A and RSU1 expression and poor prognosis in a number of malignancies, indicating that these proteins may have pro-cancer actions." (PMID 38402311, 2024). "While RSU1 has been found to play a positive role in cancer cell migration and invasion, substantial evidence suggests that RSU1 may also function as a tumor suppressor." (PMID 33853759, 2021). "Several aspects on the role of RSU1 in human cancer remain unknown and need to be addressed in the future." (PMID 32517326, 2020). "Interestingly, while several studies have been performed in vitro using various cancer cell lines, an in vivo investigation of the role of RSU1 in cancer is still missing." (PMID 32517326, 2020). "Despite the fact that there is a connection between Ras oncogene and cancer cell aggressiveness, the exact role of RSU-1 with regard to the metastatic properties of cancer cells remains unclear." (PMID 31412547, 2019). "Moreover, our knowledge of the molecular mechanism in which GDF15 and RSU-1 are involved will facilitate the identification of therapeutic targets in signaling pathways that are crucial to cancer development and progression." (PMID 31412547, 2019). "Importantly, being that GDF-15 has been associated with actin cytoskeleton reorganization, changes in matrix stiffness and cell morphology, as well as cancer progression, its regulation by RSU-1 seemed of particular importance." (PMID 30621163, 2019).
cancer (continued). "Hence, RSU-1 seems to have the potential of being both promising and clinically relevant novel marker and therapeutic target of cancer cell metastasis." (PMID 28423706, 2017). "However, Rsu1 appears to possess multiple functions in cancer, as its expression level is upregulated in certain types of cancer cells and abnormally high expression level of Rsu1 may also contribute to cancer metastasis." (PMID 33587032, 2021). "Therefore, alterations of Rsu1 level may deregulate cell adhesion and migration and influence cancer cell behavior through multiple factors." (PMID 33587032, 2021). "We found that RSU-1 silencing downregulates GDF-15, and inhibits cancer cell invasion, a phenomenon which is completely reversed by treatment of cells with human recombinant GDF-15 (hrGDF-15)." (PMID 30621163, 2019). "More specifically, there are studies showing that RSU-1 promotes cell adhesion, spreading, migration, and invasion while there is a study showing that RSU-1 inhibits cancer cell migration and invasion while its alternatively spliced truncated isoform enhances the process." (PMID 28423706, 2017). "To that regard and following RSU-1 silencing, we tested the mRNA expression of Urokinase Plasminogen Activator (UPA), a known protease involved in cancer progression and metastasis, as well as that of metalloproteinase-13 (MMP-13) known to be involved in collagen I degradation." (PMID 28423706, 2017). "The success of these therapies may in part be due to removal of aberrant hypermethylation at CpG islands within promoter regions of key cancer genes including KLF4, RUNX3, and RSU1 identified as hypermethylated in our data." (PMID 25294808, 2014). "Indeed, previous studies by us and others have shown that PINCH-1 can interact with multiple signaling proteins including ILK 37, Nck-2 60, RSU-1 61, 62, EPLIN 50, myoferlin 53 and Notch-2 55, which may also contribute to the regulation of cancer cell proliferation and survival." (PMID 35401828, 2022). "Thus, the RSU1-PHB signaling axis identified in the current study may serve as an effective target for therapeutic control of aberrant ERK signaling, anchorage-independent growth, and cancer progression." (PMID 33853759, 2021).
tumor (15 papers, 2013 to 2024). "Prior investigations have demonstrated that the association between LIMS1 and RAS suppressor protein 1 (RSU‐1) forms a synergistic complex that effectively inhibits the proliferation and migration of tumor cells." (PMID 38618967, 2024). "How RSU1 suppresses oncogenic transformation and tumor growth, however, is not well understood." (PMID 33853759, 2021). "Moreover, elimination of RSU-1 from BC tumor spheroids and hepatocellular carcinoma cells significantly inhibited their in vitro invasive capacity, suggesting that RSU-1 is a metastasis-promoting protein." (PMID 30621163, 2019). "Consistent with a tumor-promoting role of PINCH, it has been shown that PINCH interacts at focal adhesions sites with parvins, ILK, Nck1, Rsu-1, and several other partners to promote cell spreading, migration, and apoptosis resistance, features important for tumor cells." (PMID 29755929, 2018). "Tumor growth continued due to miR-409-directed inhibition of RSU1 and STAG2 tumor suppressors." (PMID 28289080, 2017). "Interestingly, RSU-1 siRNA-mediated silencing inhibited Urokinase Plasminogen Activator, and metalloproteinase-13, whereas tumor spheroids formed from RSU-1-depleted cells lost their invasive capacity in all cell lines and stiffness conditions." (PMID 28423706, 2017). "In published studies, AGRN, ITGAV, FLNC, ILK, and RSU1 were overexpressed in HCC tumor tissues, thereby promoting tumor development, metastasis, and even leading to poor prognosis, which is consistent with our findings." (PMID 36110210, 2022). "Collectively, these reports suggest that the miR-dependent regulation of RSU1 and the IPP proteins contribute to tumor progression and metastasis." (PMID 32751711, 2020). "While RSU1 depletion from MCF-7 cells resulted in an impressive and complete abrogation of cell migration, cell invasion and tumor spheroid invasion, its depletion from MDA-MB-231-LM2 cells dramatically promoted all three pro-metastatic properties." (PMID 32517326, 2020). "Ras suppressor-1 (Rsu-1) is a leucine-rich repeat (LRR)-containing protein that is crucial for regulating cell adhesion and is involved in such physiological and pathological processes as focal adhesion assembly and tumor metastasis." (PMID 33891945, 2021). "Furthermore, RSU1, a suppressor of Ras-dependent oncogenic transformation, was reported to interact with LIMS1, and was attributed to inhibiting cell proliferation and invasion in tumor cells including HCC." (PMID 35805200, 2022). "Notably, in E-SOBP cells, we observed upregulation CASP8 molecular switch for apoptotic pathway, the anti-proliferative tumor regulator CDKN1C, and tumor suppressor and Ras Suppressor Protein 1, which is also a strong tumor suppressor gene in E-SOBP treated cells." (PMID 34885223, 2021). "Out of the 24 tumor tissue 6 tumor tissues (25%) were completely negative for Rsu-1 while 17 of the tumors were moderately positive for Rsu-1 and only 1 was strongly positive for Rsu-1." (PMID 24058607, 2013).
kidney disease (1 paper, 2021). "Therefore, the RSU1 gene might be associated with kidney disease." (PMID 34946851, 2021).
myopathies (1 paper, 2018). "Mutations in the genes encoding RSU1, tensin and vinculin have not been linked to muscle myopathies, but mutations in filamin are linked to myofibrillar myopathies." (PMID 30028294, 2018).
RSU1 also shares sentences with these, for which no sentence is quoted: fibrosarcoma (2 papers); neuroblastoma (2); brain tumor (1); Cognitive impairment (1); endothelial dysfunction (1); Familial adenomatous polyposis (1); infection (1); polyposis (1); promyelocytic leukemia (1).